TNF (tumor necrosis factor)
Diseases named in the same sentence as TNF in open-access papers (continued):
Sharing a sentence is not in itself a finding about the gene and the disease.
rheumatoid arthritis (continued). "Studies in Taiwan have shown a 2.28-fold increase in the risk of tuberculosis in patients with rheumatoid arthritis than that in the general population, while patients treated with TNF-α inhibitors were at higher risk of developing tuberculosis than those treated with other medications." (PMID 34776944, 2021). "This could be of particular relevance in the treatment of pathologies associated with a relevant increase in TNF, such as rheumatoid arthritis, Crohn's disease, and OA." (PMID 34484347, 2021). "In rheumatoid arthritis, persistent stimulation by inflammatory cytokines such as TNF and IL-6 causes the formation of inflammatory synovial granulation tissue, which is characterized by the accumulation of lymphocytes, synovial proliferation, and angiogenesis." (PMID 33802804, 2021). "MiR-26b has been associated to RA and inflammation where inhibition of miR-26b in rheumatoid arthritis fibroblast-like synoviocytes (RAFLS) causes increased levels of TNF-α, IL-1β, and IL-6, while miR-26b mimics mediate downregulation of the same proinflammatory cytokines." (PMID 33210166, 2021). "hTNF Tg mice served as an excellent model for associated disorders, such as progressive rheumatoid arthritis, although physiological relevance of using these mice in order to delineate the in vivo effects of systemic TNF inhibition on other functions was limited." (PMID 34054827, 2021). "Moreover, several autoimmune conditions are linked with the dysregulation or elevated plasma level of TNF-α, e.g., rheumatoid arthritis, Alzheimer’s, depression, inflammatory bowel diseases, ankylosing spondylitis, psoriasis, cancer, and ulcerative colitis." (PMID 33671607, 2021). "Our findings suggest that TLR4/TNF-α might be a potential target to suppress bone loss associated with inflammatory bone diseases, including periodontitis, rheumatoid arthritis, and osteoporosis." (PMID 33765924, 2021). "Meanwhile, lysosome autophagy signaling pathways stimulated by hTNF-α were inhibited by FVH1-1, which down-regulated the expression of LC3II/LC3I and up-regulated the expression of P62, indicating that the autophagy linked with TNF-α-induced apoptosis in response to rheumatoid arthritis." (PMID 32880389, 2020). "TNF is a pro-inflammatory cytokine critical for host defense against bacterial, viral, and parasitic infections, yet excessive production of TNF has been causally linked with multiple autoimmune and inflammatory diseases such as rheumatoid arthritis, IBD, and diabetes." (PMID 33150865, 2020). "While physiological inflammation is locally protective, pathological inflammation caused by persistent and unregulated TNF levels cause chronic tissue damage and drive the pathogenesis of inflammatory disease including rheumatoid arthritis, Crohn’s disease, and inflammatory bowel disease." (PMID 32309522, 2020). "Furthermore, pre-diagnostic levels of plasma CRP and IL-6 are associated with a higher risk of Crohn’s disease; and TNFR2 level, a proxy for TNF-α, is associated with higher risk of rheumatoid arthritis up to 12 years prior to disease symptoms." (PMID 33259491, 2020). "In rheumatoid arthritis, studies have shown that over time 30–40% of the patients may lose response to anti-TNF treatment (secondary loss of response)." (PMID 33193432, 2020). "We confirmed that higher TNF levels were strongly associated with established TNF-driven diseases (rheumatoid arthritis and inflammatory bowel disease) which added strong support to the validity of the genetic instrument used and the reliability of our findings." (PMID 32805626, 2020). "To validate the instrumental variables, we assessed whether genetically predicted TNF levels were associated with higher risk of rheumatoid arthritis and inflammatory bowel disease." (PMID 32805626, 2020). "In this light, our model may be used to quantify the effects of anti-cytokine therapy (e.g. anti-TNF therapeutics for rheumatoid arthritis) on the risk of cardiovascular events." (PMID 32868834, 2020).
rheumatoid arthritis (continued). "TNF-α-mediated inflammation contributes to chronic low-grade inflammation associated with advanced age and is connected with many age-related diseases such as cardiovascular disease and rheumatoid arthritis." (PMID 32551387, 2020). "However, chronic exposure to adverse metabolic and hemostatic risk factors, obesity, or disease states such as kidney disease or rheumatoid arthritis are all associated with a systemic inflammatory condition and elevated circulating levels of TNFα." (PMID 32749215, 2020). "Similar to rheumatoid arthritis, inflammatory cytokines, such as IL-1 and TNFα, are likely deeply implicated in the onset of osteoarthritis, although, it remains controversial whether osteoarthritis is an inflammatory disease." (PMID 32079226, 2020). "In Crohn's disease or rheumatoid arthritis, this receptor triggers the production of cytokines associated with inflammation, interleukin-18 or interleukin-1β (IL-1β), and tumor necrosis factor-α (TNF-α)." (PMID 32566102, 2020). "Until the advent of tocilizumab, TNFα was thought to be the main cause of the rheumatoid arthritis." (PMID 32743515, 2020). "However, in patients with rheumatoid arthritis or osteoarthritis, the GG genotype and G allele of rs361525 were associated with increased TNFα expression, respectively." (PMID 30890897, 2019). "The proinflammatory cytokine TNF-α has been extensively implicated in the pathogenesis of proliferative synovitis and bone resorption and is a major target for the treatment of inflammatory arthritis, such as rheumatoid arthritis (RA)." (PMID 31261789, 2019). "Rheumatoid arthritis (RA) is an autoimmune disease that affects the synovial cavity of joints, and its pathogenesis is associated with an increased expression of pro-inflammatory cytokines, namely tumour necrosis factor-alpha (TNF-α)." (PMID 30965588, 2019). "In the analysis of patients using anti-TNF-α antibodies against underlying diseases such as rheumatoid arthritis (RA) or Crohn’s disease, disseminated TB, past TB infection, and corticosteroid use at the time of diagnosis have been reported as the risk factors of IRIS development." (PMID 31905985, 2019). "As might be expected with such a broad spectrum of cellular effects and complex signalling pathways, TNF has also been implicated in a number of disease states, such as rheumatoid arthritis, ankylosing spondylitis, and Crohn’s disease." (PMID 30755793, 2019). "Similarly, inflammatory cytokines such as IL-6, IL-18, and TNF-alpha, which are typically elevated in rheumatoid arthritis, have been associated with cardiovascular disease." (PMID 30886961, 2018). "In fact, TNF has been reported that it is associated with the pathogenesis of Rheumatoid Arthritis." (PMID 30713550, 2018). "Therefore, there is a clear need for orally available, well-tolerated, inexpensive drugs that block the production of TNF associated with pathological inflammation in rheumatoid arthritis and related conditions." (PMID 30090063, 2018). "KEGG pathway analysis further revealed the enrichment of DE genes in the chemokine signaling pathway, cytokine–cytokine receptor interaction pathway, TNF signaling pathway, and rheumatoid arthritis pathway, confirming the pathogenic features of CD27+IgD+ B cells in RA." (PMID 29628928, 2018). "However, there are substantial risks with TNF inhibitors, including increased risk of development of solid cancers in patients with rheumatoid arthritis." (PMID 29861860, 2018). "An increasing focus on TNF-α-induced angiogenesis has been implicated not only in atherosclerotic plaque but also in the progression of cancer, wet age-related macular degeneration and rheumatoid arthritis." (PMID 30125282, 2018).
rheumatoid arthritis (continued). "Anti-TNF therapy has been theoretically linked with a propensity for malignancy, due to the suppression of TNF, and a meta-analysis in 2006 reported a 3-fold increased risk of malignancy for patients with rheumatoid arthritis undergoing anti-TNF (infliximab/adalimumab) treatment." (PMID 30065229, 2018). "In addition to its role in infection, the cytokine TNF has been linked to debilitating fatigue in rheumatoid arthritis patients, altered clock gene expression and prolonged rest periods in mice." (PMID 29253904, 2017). "Increased bone resorption by activated osteoclasts can be caused by systemic alterations such as the upregulation of osteotropic or osteoclastogenic cytokines, including RANKL, TNFα, and IL-6, which in turn cause bone-destructive diseases, including rheumatoid arthritis (RA)." (PMID 28724396, 2017). "TNF-α has also been implicated in increased cardiovascular risk, and it is central to the pathophysiology of cancer and chronic inflammatory conditions, including inflammatory bowel diseases, rheumatoid arthritis and psoriasis." (PMID 28076613, 2017). "Two conditions known to be associated with anti-TNF antibody treatment of rheumatoid arthritis, namely increased infection with M. tuberculosis and occurrence of Merkel cell carcinomas, have both been identified as being kept at bay by TNF-secreting lymphocytes, respectively." (PMID 28946707, 2017). "In addition, pioglitazone treatment modestly ameliorates rheumatoid arthritis (RA) activity by preventing bone loss and suppresses plasma levels of cytokines, including TNF-α, IL-1β, and IL-6." (PMID 27548145, 2016). "TNF-α and IL-6 have been implicated in autoimmune diseases including rheumatoid arthritis." (PMID 27422559, 2016). "As a master regulator of pro-inflammatory cytokines such as IL-1β, IL-6 and GM-CSF, over expression of TNF-α causes a variety of chronic inflammatory diseases including rheumatoid arthritis, Crohn’s disease, psoriatic arthritis, ankylosing spondylitis and psoriasis, and so on." (PMID 27658047, 2016). "TNF inhibitors, such as Adalimumab, seem to be able to arrest systemic bone loss assessed by bone mineral density and bone turnover markers in rheumatoid arthritis; nevertheless, evidences of the effect of anti-TNF treatment in preventing fractures are still scarce." (PMID 27088019, 2016). "It has been supposed that anti-TNF-α treatment could cause an inhibition of bone turnover mediated by a reduction of RANKL which could already be shown in patients with rheumatoid arthritis and anti-TNF-α therapy." (PMID 27088019, 2016). "TNF-α is such a cytokine which has been implicated to play a key role in the pathogenesis of atherosclerosis and other chronic inflammatory diseases like asthma, chronic obstructive pulmonary disease, rheumatoid arthritis and inflammatory bowel disease." (PMID 27467817, 2016). "Tumor necrosis factor (TNF) is an important and pleiotropic cytokine which is also involved in the pathogenesis of inflammation in rheumatoid arthritis (RA), and RA treated with anti-TNF agents with a subsequent increase in hypertension risk is also observed in clinical trials." (PMID 25860222, 2015). "The many genetic studies performed in recent years showed that genes such as interleukin 23 receptor (IL23R) and IL12B and tumor necrosis factor alpha (TNFα) are closely associated with psoriasis and related diseases such as rheumatoid arthritis, psoriatic arthritis, and Crohn's disease." (PMID 26613086, 2015). "In addition, TNFα is also known to play a pathogenic role in several autoimmune diseases, including rheumatoid arthritis and inflammatory bowel disease, in which TNFα-blocking therapies have been successful." (PMID 26779181, 2015). "Overproduction of TNF-α in rheumatoid arthritis patients has been linked to increased ROS." (PMID 25705127, 2015).
rheumatoid arthritis (continued). "In addition, this region also harbors GWAS associations with traits ranging from TNFα response in patients with rheumatoid arthritis to hematologic traits." (PMID 25147783, 2014). "Similarly, a clinical study has shown that fish oil supplementation in rheumatoid arthritis patients was associated with decreased production of IL-1 and TNF-α." (PMID 23951199, 2013). "In addition, TNFα, another Th1 cytokine, is of almost equal importance, as treatment with biologics (e.g., anti-TNFα antibody) for inflammatory disorders such as rheumatoid arthritis has caused reactivation of TB in some individuals." (PMID 23544075, 2013). "However, overproduction of TNF-α has been associated with autoimmune disorders, such as rheumatoid arthritis and Crohn's disease." (PMID 23985898, 2013). "However, even when excluding individuals treated with TNF antagonists, studies have observed an increased risk for TB in patients with rheumatoid arthritis." (PMID 23557090, 2013). "Anti-tumor necrosis factor alpha (anti-TNF) drugs are very effective for the treatment of rheumatoid arthritis but may increase the risk of serious bacterial infections." (PMID 24498926, 2013). "Similarly, in a rheumatoid arthritis animal model, lipopolysaccharide (LPS) treatment causes similar pathological symptoms via increased TNF-α production." (PMID 23468959, 2013). "TNF-α is a major cytokine implicated in rheumatoid arthritis." (PMID 21611196, 2011). "Rheumatoid arthritis (RA) is a chronic inflammation disease characterised by hypertrophy of the synovial membrane, ultimately causing joint damage due, in part, to the sustained production of inflammatory cytokines such as TNFα, IL-1β and IL-6." (PMID 21914218, 2011). "Tumor necrosis factor (TNF) is one of the important cytokine that has long been considered as a pathological factor implicated in the pathology of dozens of human diseases, including septic shock, cancer, rheumatoid arthritis, malaria and other afflictions." (PMID 20497537, 2010). "The inflammatory cytokines, TNF-α, IL-1β, IL-6 and IL-17 are all regulatory factors responsible for the initiation, perpetuation and destructive capacity of the rheumatoid arthritis synovium and all four have been implicated in recruitment of inflammatory cells to the joint." (PMID 19409094, 2009). "IL-7 has also been suggested to play a role in rheumatoid arthritis based upon the observation of increased levels of the cytokine in this patient population, its ability to induce TNFα and induction of bone loss by stimulation of RANKL-dependent osteoclastogenesis." (PMID 18234077, 2008). "In contrast to this view in a recent meta analysis study it has been shown thatan increased risk of serious infections and a dose-dependent increased risk of malignancies in patients with rheumatoid arthritis treated 12 weeks with two anti-TNF antibodies (infliximab and adalimumab)." (PMID 17034639, 2006). "However, when patients with rheumatoid arthritis, whose mortality is associated with IR‐associated metabolic disorder, were treated with a TNF inhibitor, it significantly improved their insulin response, implying that TNF action is more complex in clinical contexts." (PMID 38874196, 2025). "TNFα has been associated with the pathogenesis of several autoimmune diseases (ADs) including rheumatoid arthritis (RA), inflammatory bowel disease (IBD), psoriasis (PS), and ankylosing spondylitis (AS), serving as a driver of chronic inflammation." (PMID 40469293, 2025). "Therefore, it is necessary to correlate the results shown in the present study with those obtained from research involving analysis of the variants in the TNFα and IL-6 genes intended for other diseases, including rheumatoid arthritis and dengue, which have similar characteristics to CHIKF." (PMID 41472214, 2025).
rheumatoid arthritis (continued). "Excessive production of TNF is associated with the development of RA, and biological therapy with TNF inhibitors has radically changed the treatment of rheumatoid arthritis, and is an integral part in the management." (PMID 39801258, 2025). "TNF inhibitors have also been shown tostrengthen the overall pathological characteristics with rheumatoid arthritis(RA) and psoriasis who are at high cardiovascular risk, in addition to thesefindings in atherosclerosis patients." (PMID 40160593, 2025). "Dendritic cells (DCs) play a central role in the immunopathogenesis of rheumatoid arthritis (RA), yet their regulation by tumor necrosis factor alpha (TNF) and associated receptors remains poorly characterized." (PMID 40649852, 2025). "This study elucidates that TNF-α drives macrophage-derived itaconate production to epigenetically suppress osteoclast hyperactivation through Tet2 inhibition, establishing itaconate and its derivative OI as novel therapeutic agents against rheumatoid arthritis -associated bone destruction." (PMID 40500265, 2025). "Results obtained from observational studies indicate that the use of TNF-α inhibitors in rheumatoid arthritis (RA) patients is associated with a lower DM incidence and better metabolic control compared to non-biological agents." (PMID 38776022, 2024). "In Rheumatoid Arthritis (RA), persistent TNF signals cause aberrant activation of synovial fibroblasts (SFs), the resident cells crucially involved in the inflammatory and destructive responses of the affected synovial membrane." (PMID 39122678, 2024). "Additionally, lower Klotho expression is seen in T-helper cells of elderly individuals and rheumatoid arthritis patients with joint inflammation, correlating with increased proinflammatory tumor necrosis factor-alpha (TNF-α) levels and associated renal fibrosis." (PMID 40799848, 2024). "In particular, tumor necrosis factor-alpha (TNFa) is a pleiotropic cytokine, characterized as a main regulator of inflammatory responses, while its presence in high amounts is associated with the pathogenesis of several inflammatory diseases, like Crohn’s disease and rheumatoid arthritis." (PMID 38203178, 2023). "The joint inflammation caused by TNF-alpha activity has been investigated in patients with OA and rheumatoid arthritis (RA), illustrating it as a promising target to be considered in RA treatment." (PMID 36873347, 2023). "We aimed to determine the risk of herpes zoster (HZ) in Korean rheumatoid arthritis (RA) patients on tofacitinib compared with tumor necrosis factor inhibitor (TNFi) treatment." (PMID 37188765, 2023). "Diagnostic challenges arise due to the low incidence of TNF-a antagonist-induced granulomatosis, wide variability in exposure duration at symptom onset, and possible presence of symptoms due to the underlying disease (e.g., rheumatoid arthritis or Crohn’s disease)." (PMID 37250639, 2023). "In 2020, the Global Rheumatology Alliance reported that patients with rheumatic diseases, such as rheumatoid arthritis (RA), who were being treated with TNFα inhibitors had a reduced risk of hospitalization from COVID-19." (PMID 37515185, 2023). "And it turned out that Jinwujiangu prescription on RA was highly associated with the signaling pathways of TNF, IL-17, NF-κB, Toll-like receptor, and rheumatoid arthritis." (PMID 36816744, 2023). "Tumor necrosis factor (TNF)-α is a pleiotropic cytokine implicated in the etiology of several autoimmune diseases, including rheumatoid arthritis (RA)." (PMID 36012570, 2022). "Elevated ERK1/2 activity has been found in inflamed joints of patients with the autoimmune disease rheumatoid arthritis (RA) and ERK1/2 inhibitors show therapeutic promise by reducing levels of RA-associated inflammatory cytokines including TNF, IL-1 and IL-6." (PMID 36281999, 2022).